MUC1 (mucin 1, cell surface associated)
Diseases named in the same sentence as MUC1 in open-access papers (continued):
Sharing a sentence is not in itself a finding about the gene and the disease.
ovarian carcinoma (continued). "These events may include childhood mumps, puerperal mastitis, and tubal ligation—each shown to raise anti-MUC1 antibodies and each shown to lower the risk for ovarian cancer in case–control studies." (PMID 37869082, 2023). "Importantly, there are prospective data from two studies suggesting that natural antibodies against MUC1 can lower the risk for ovarian cancer." (PMID 37869082, 2023). "Pointing out that the presence of anti-MUC1 antibodies leads to reduced risk for ovarian cancer, the corollary follows that their absence may increase the risk for cancer." (PMID 37869082, 2023). "Anti-MUC1 IgG1 antibodies have also shown a positive association with ovarian cancer." (PMID 35380164, 2022). "High expression levels of the tumor-associated antigen MUC1 have been correlated with tumor aggressiveness, poor response to therapy, and poor survival in several tumor types, including breast, pancreatic, and epithelial ovarian cancer." (PMID 32429033, 2020). "Similarly, MUC-1 specific tumor infiltrating/associated CTL were detected in ovarian cancer patients." (PMID 27323861, 2016). "The high levels of MUC1 are associated with an advanced cancer grade/stage of ovarian carcinoma." (PMID 26492273, 2015). "Therefore, we examined the association between a targeted set of single nucleotide polymorphisms (SNPs) in MUC16 (rs2547065, rs1559168, rs12914471, rs2121133) and MUC1 (rs2070803, rs4072037, rs1045253) in relation to ovarian cancer risk and survival." (PMID 24551091, 2014). "It has been hypothesized that women who have undergone events that trigger an immune response to MUC1 have a decreased risk of ovarian cancer." (PMID 22587442, 2012). "This may be achieved by transducing tumor cells with viral vectors transfected with genes encoding immunogenic antigens, such as mucin 1 (MUC1), which is a transmembrane glycoprotein that is overexpressed in many cancers, including prostate, breast, and ovarian cancer." (PMID 37681880, 2023). "However, there may be effects of MUC16 rs12984471 on survival and MUC1 rs4072037 on risk for histologic types of ovarian cancer other than invasive serous." (PMID 24551091, 2014). "Tn‐MUC1 is highly expressed in most cancers, accounting for 100% of stomach, 71% of colon, 75% of lung, 83% of breast, and 80% of ovarian cancers, although the number of such cases is small." (PMID 40844495, 2025). "Exploratory markers FOLR1 and MUC1 had subtle increases for cancer groups, with early-stage ovarian cancer samples having the smallest effects." (PMID 40801326, 2025). "The pH-sensitive QD-MUC1-DOX conjugate released DOX from the payload only after the QD-MUC1-DOX had been internalized into MUC1-overexpressing ovarian cancer cells to avoid any MDR, which ultimately improved the efficacy of the therapeutics." (PMID 40688030, 2025). "Aberrant expression of MUC1 has been noted in a majority of epithelial ovarian cancers, with studies indicating overexpression in 90–100% of serous carcinomas." (PMID 40277517, 2025). "The microcantilever has been shown to be efficacious in detecting MUC1, which is overexpressed in ovarian cancer." (PMID 40277517, 2025). "The VNp-anti-Muc-1 band was significantly more intense in the extract from A2780, which is consistent with the fact that Muc-1 is a biomarker upregulated in ovarian cancer cells." (PMID 39965660, 2025). "For cohort 2, CA125, HE4, and MUC1 were increased in early-stage ovarian cancer whereas FOLR1 was equivalent between early-stage ovarian cancer and controls." (PMID 40801326, 2025). "According to certain theories, MUC1 contributes to the growth of ovarian cancers and the unfavorable prognosis of patients." (PMID 38540735, 2024). "Up to 90% of breast tumors, approximately 70%–90% of pancreatic ductal adenocarcinomas and ovarian cancers (OvCas), 50%–80% of lung adenocarcinomas and colorectal cancer, and 30%–70% of prostate cancers reported to express abnormal MUC1 expression." (PMID 38910324, 2024).
ovarian carcinoma (continued). "The positive expression rate of MUC1 was found to be 95.0% (57/60) in research including 60 primary ovarian cancer tissue specimens that were paraffin-embedded and sectioned." (PMID 38540735, 2024). "A refinement of this study was achieved through the use of proximity-ligation assay (PLA), in which aberrant glycoforms (Tn, STn, and T) of MUC16 and MUC1 in ovarian cancer tissue were detected." (PMID 37455827, 2023). "Further, in a study reported by Savla, the MUC-1 doxorubicin conjugated quantum dots showed similar results in the MUC-1 expressing A2780/AD ovarian cancer cells." (PMID 36615606, 2023). "Of note, several potential biomarkers show a significant overexpression in ovarian cancers, such as MUC-1 glycoprotein." (PMID 36615606, 2023). "In conclusion, the synthesized MMSNP-SUN-MUC-1 nanosystem serves as a unique multifunctional targeted delivery system to combat the MUC-1 overexpressing ovarian cancer cells." (PMID 36615606, 2023). "MUC1 has been shown to be expressed in CTCs in ovarian cancer, including EMT-like CTCs that were enriched by platinum-based therapy." (PMID 38065965, 2023). "It represents a distinct epitope on the mucin MUC1, and its elevated levels have been detected in ovarian cancer." (PMID 37238197, 2023). "It indicates that mir-145-5p can block the invasion and metastasis of ovarian cancer cells by mediating the MUC1/E-cad signal pathway." (PMID 35340746, 2022). "In other studies, FeNPs coated with monoclonal antibodies were used to detect ovarian cancers overexpressing mucin-1 (MUC-1)." (PMID 36557793, 2022). "Conversely, the effect of mir-145-5p was unregulated or inhibited by MUC1, suggesting that MUC1 is the target gene of mir-145-5p in ovarian cancer." (PMID 35340746, 2022). "On the other hand, we showed that sialic acid on MUC1 potentially exerts inhibitory effects on the peritoneal dissemination of clear cell-type ovarian cancer cells in a mouse model." (PMID 35743163, 2022). "mir-145-5p can inhibit the expression of MUC1 protein through complementarily binding with MUC1, so that can enhance the expression of E-cad, which is a marker protein of ovarian cancer." (PMID 35340746, 2022). "By monitoring the tumor burden and the survival of mice, we confirmed the inhibitory action of MUC1-bearing sialoglycans against peritoneal dissemination of ovarian cancer cells in vivo." (PMID 34641504, 2021). "From the 55 ovarian cancer samples that were analysed, 54 of those samples expressed MUC1/Y, proposing that MUC1/Y is a strong candidate for indicating the presence of malignancy." (PMID 34452200, 2021). "In ovarian cancer progression, the detailed roles and mechanisms of action of MUC1 with unique glycosylation in tumor development and dissemination have yet to be fully understood." (PMID 34641504, 2021). "The present study was thus undertaken to assess the role of sialylation of MUC1 oligosaccharides in peritoneal dissemination of ovarian cancer cells under in vivo and in vitro experimental settings." (PMID 34641504, 2021). "The role of sialic acids on MUC1 in peritoneal dissemination of ovarian cancer cells was investigated." (PMID 34641504, 2021). "A reliable 10-gene ferroptosis signature (HIC1, ACSF2, MUC1, etc.)for the diagnosis of ovarian cancer was identified." (PMID 35071242, 2021). "MUC1 is commonly overexpressed in various epithelial adenocarcinomas such as lung, liver, colon, breast, pancreatic, and ovarian cancer." (PMID 34207342, 2021). "Specifically, a 10-gene signature (HIC1, ACSF2, MUC1, etc.)was developed for the diagnosis of ovarian cancer with high sensitivity using LASSO regression." (PMID 35071242, 2021). "The expression of the ovarian carcinoma marker MUC1 is also decreased and suggests a more undifferentiated phenotype." (PMID 33671478, 2021). "In the paper, the authors demonstrated that MUC1 overexpresses in the majority of ovarian carcinomas and contributes to the metastasis process, promotes tumor formation and metastasis." (PMID 34149811, 2021).
ovarian carcinoma (continued). "We also revealed that MUC1 with sialyl-T glycans inhibits peritoneal dissemination of ovarian cancer cells in vivo, as shown in immune compromised mice, uncovering an unexpected role of MUC1 with sialylated O-glycans." (PMID 34641504, 2021). "Circular RNA WHSC1 contributes to progression of ovarian cancer by modulating hTERT and MUC1 through targeting exosomal miR-1182 and miR-145." (PMID 34690112, 2021). "MUC1 undergoes various glyco-modifications during ovarian cancer progression, and is also overexpressed in other adenocarcinomas and haematological malignancies." (PMID 32937961, 2020). "Selectin ligands that have been targeted for therapeutic intervention in ovarian cancer include MUC1 and MUC16." (PMID 32785160, 2020). "From 2000 to 2015, there were 13 clinical trials with 148 patients receiving DC immunotherapy for ovarian cancer targeting antigens that included MUC1, MUC16, HER2, and FOLR1, with variable and inconsistently reported results." (PMID 32937961, 2020). "The results of the HOUP hub genes confirmed that the expression levels of TNF, ESR1, CDK1, CXCR4 and MUC1, indicating these 5 hypomethylated genes were activated in ovarian cancer development." (PMID 32192517, 2020). "To wit, patients with metastatic, treatment-resistant ovarian cancer frequently present elevated levels of MUC1, with >90% producing antibodies against the antigen." (PMID 32429033, 2020). "Moving on to the in vivo experiments, the data show that [89Zr]Zr-DFO-AR20.5 is capable of clearly visualizing MUC1-expressing tumor tissue in mice bearing both subcutaneous and orthotopic ovarian cancer xenografts." (PMID 32429033, 2020). "MUC1 is highly expressed in primary epithelial ovarian cancer as well as the vast majority of cases of metastatic disease." (PMID 32429033, 2020). "Subsequently, the in vitro behavior of DFO-AR20.5 was evaluated via flow cytometry experiments with MUC1-expressing SKOV3 human ovarian cancer cells, ultimately confirming the ability of the immunoconjugate to bind its molecular target." (PMID 32429033, 2020). "In the manuscript at hand, we report the synthesis, characterization, and in vivo evaluation of [89Zr]Zr-DFO-AR20.5 in two murine models of MUC1-expressing ovarian cancer." (PMID 32429033, 2020). "5E5 antibody, which recognizes Tn/sialyl-Tn epitopes of MUC1, was highly expressed in ovarian carcinoma, suggesting a role of truncated glycans." (PMID 32075174, 2020). "CAN-003, a phase II study on 63 patients with epithelial ovarian cancer, administered the Mucin-1 (MUC1)-derived dendritic cell vaccine Cvac, with notable increases in progression-free survival and objective survival compared to a mock vaccine (NCT01068509)." (PMID 30646939, 2019). "GalNT6 is up-regulated in breast and ovarian cancer initiating the O-glycosylation of MUC1, which we identified as a major ligand of CLEC10A." (PMID 31455323, 2019). "In ovarian cancer, MUC1 is highly expressed compared to normal tissues and participates in cellular transformation and tumorigenicity." (PMID 31666098, 2019). "AR20.5 (OncoQuest Inc., Edmonton, AB, Canada), is a murine anti-MUC1 monoclonal antibody (IgG1) generated with MUC1 from an ovarian cancer patient." (PMID 29857542, 2018). "The paired expression of STON2 and MUC1 in ovarian cancer specimens was also detected revealing the prognostic value of STON2 expression to be highly dependent on MUC1 expression." (PMID 30518424, 2018). "STON2 knockdown promotes stem-like properties in ovarian cancer cells and its overexpression suppresses MUC1-induced sphere formation in OCSCs, in which DNMT1-mediated methylation in the promoter region of MUC1 has been confirmed to be modulated by STON2." (PMID 30518424, 2018). "STn is found on a number of proteins expressed on ovarian cancer cell surface including proteins such as MUC1 and CD44." (PMID 30052649, 2018).
ovarian carcinoma (continued). "In agreement with our results, it has recently been reported that ovarian cancer cell lines increase MUC1 expression when cultured in 3D conditions." (PMID 30380716, 2018). "The reason for such an inconsistency is unclear, but our paper certainly represents a fairly comprehensively exploration of the prognostic value of STON2 expression and MUC1 expression in ovarian cancer." (PMID 30518424, 2018). "High expression levels of MUC1 are well documented as correlated with metastasis, chemoresistance, and the survival of ovarian cancer cells." (PMID 30518424, 2018). "Pyrosequencing data also revealed that the methylation level was reduced in the MUC1 promoter region in STON2 or DNMT1 knocked down ovarian cancer cells." (PMID 30518424, 2018). "A study using MUC1 transgenic mice for evaluation of the effect of an anti-PD-L1 antibody on the growth of an aggressive MUC1 expressing murine ovarian cancer cell line (2F8) is illuminating." (PMID 29784646, 2018). "We also analyzed the correlation of MUC1 expression with clinicopathological characteristics, and prognosis of ovarian cancer." (PMID 30518424, 2018). "STn is expressed on ovarian cancer biomarkers including CA-125 (MUC16) and MUC1, and elevated serum levels of STn in ovarian cancer patients correlate with lower five-year survival rates." (PMID 30052649, 2018). "We found that, among three ovarian cancer cells in this study, MUC1 protein was only expressed in OVTW59 cells." (PMID 28388560, 2017). "Using MVs derived from ovarian cancer ascites fluid as well as from a MUC1 engineered tumor cell line, we show that MV internalization modifies DC phagosomal microenvironment, inducing accumulation of reactive oxygen species (ROS) and alkalinization." (PMID 28993771, 2017). "Our findings also have implications in treating other cancers, as MUC1 has been shown to be upregulated in many PTX-resistant tumors including ovarian cancer and gastric cancer based on ONCOMINE database." (PMID 28796259, 2017). "MUC1-specific CD8+ T cells were expanded from PBMCs of an ovarian cancer patient, previously vaccinated with the HLAI-A2-restricted MUC1159-167 peptide." (PMID 28993771, 2017). "An altered form of the tumor antigen MUC1 is frequently expressed in ovarian cancer, and immunity against MUC1 is formed by mumps infection, which results in the observed inverse correlation between mumps and ovarian cancer." (PMID 28534024, 2017). "The AdnaTest is based on the immune-magnetic isolation of ovarian cancer CTCs using antibodies against MUC1 and EpCAM." (PMID 29290959, 2017). "In conclusion, the preliminary data of this study indicate that MUC1 is a suitable target for ovarian cancer imaging, and anti-MUC1 antibody conjugated with fluorescent dyes is promising for further imaging applications." (PMID 25663888, 2015). "While multiple MUC-1 vaccines are now in development, CVac® (Prima BioMed) is the leading candidate for treatment of ovarian cancer." (PMID 25806106, 2015). "The present study aimed to evaluate the feasibility of in vivo molecular imaging using fluorescent labeled antibodies against MUC1 for the detection of ovarian cancer." (PMID 25663888, 2015). "The tumors overexpress human MUC1 similarly to the human disease and respond to MUC1 immunotherapy, further strengthening the evidence on its efficacy as a target in ovarian cancer." (PMID 25078979, 2014). "Li Wang and others checked the in vitro effect of anti-MUC1 C595 alone and in combination with docetaxel on survival of epithelial ovarian cancer (EOC) cell lines." (PMID 24639126, 2014). "MUC1 has been shown to be essential for ovarian cancer tumorigenesis in mouse models and is over expressed in approximately 90–100% of serous carcinomas." (PMID 24551091, 2014). "Flow cytometric analysis was performed to confirm the availability and quantitative analysis of desired ovarian cancer cell surface antigen (MUC1)." (PMID 24194685, 2013).
ovarian carcinoma (continued). "The aim of this study is to find out the development and application of MUC1-expressing ovarian cancer (OVCAR3) by C595 monoclonal antibody-conjugated superparamagnetic iron oxide nanoparticles (SPIONs) using MR imaging." (PMID 24194685, 2013). "The strategy is to use SPIONs attached to C595 mAb that binds to the MUC1, to specifically detect ovarian cancer cells." (PMID 24194685, 2013). "In this study, the expression of MUC1 and the Lewis y antigen in ovarian cancer tissues was detected using immunohistochemistry and, subsequently, correlated with tumor chemoresistance and patient prognosis." (PMID 23708102, 2013). "The expression of MUC1 and Lewis y antigen in ovarian cancer tissues was detected using immunohistochemistry and correlated with chemoresistance." (PMID 23708102, 2013). "The aim of this study was to analyze the correlation and clinical significance between the expression of Mucin-1 (MUC1) and the Lewis y antigen with chemoresistance in ovarian epithelial cancers." (PMID 23708102, 2013). "Among the 92 cases of ovarian cancer, MUC1 expression is primarily located on the cell membrane and cytoplasm." (PMID 23708102, 2013). "Spearman’s rank correlation analysis shows that MUC1 protein expression positively correlates with Lewis y antigen expression in ovarian epithelial cancer (rs = 0.26, p < 0.05)." (PMID 23708102, 2013). "The results of flow cytometry, Prussian blue staining, signal intensity, biodistribution and measurement of iron uptake by cells showed high targeting and affinity of SPIONs-C595 to MUC1 positive ovarian cancer cells (OVCAR3)." (PMID 24194685, 2013). "An increase in MUC1 expression is associated with the chemoresistance of ovarian cancer; thus the expression of MUC1 can be used to predict ovarian cancer chemoresistance." (PMID 23708102, 2013). "In this study, we increased the sample size, expanded the pathological type, added a group sensitive to chemotherapy and confirmed that MUC1 expression is a reliable index for predicting chemoresistance in ovarian cancer." (PMID 23708102, 2013). "This is the first study to show that the expression of MUC1 and the Lewis y antigen are increased in chemoresistant ovarian cancer." (PMID 23708102, 2013). "In this study, the production and evaluation of magnetic nanoprobe (SPIONs-C595) and its application as MR imaging contrast agent for targeted molecular imaging of MUC1-expressing ovarian cancer cells was investigated." (PMID 24194685, 2013). "Our results from IHC indicate a prognostic relevance of MUC1 in ovarian carcinoma when evaluated by the VU4H5 antibody." (PMID 23241107, 2012). "Another aim was to evaluate the MUC1 expression by IHC in a different cohort of ovarian carcinoma patients with respect to grade, stage and survival." (PMID 23241107, 2012). "There were significant differences in MUC1 expression between serous, clear cell, endometrioid or mucinous forms of ovarian carcinoma." (PMID 23241107, 2012). "Mean overall survival for patients with serous MUC1 positive ovarian carcinoma was 4.98 years (range: 3.82-6.13) compared to 8.77 years (range: 5.69-11.85) for patients with negative expression, evaluated by VU4H5 (p=0.032)." (PMID 23241107, 2012). "Our study shows a worse outcome for patients with high expression of MUC1 in ovarian carcinoma and thus supports its potential for targeted therapy." (PMID 23241107, 2012). "One aim of this study was to compare the concentrations of MUC1 in a cohort of patients with either benign or malignant ovarian tumours detected by CA 15–3 and CA 27.29." (PMID 23241107, 2012). "MUC1 serum levels are increased during pregnancy and, similar to ovarian cancer, the circulating mucin is less heavily sialylated than the mucin derived from normal tissues." (PMID 24212946, 2011). "A natural immune response to MUC1 seems insufficient to affect the course of disease in patients with epithelial ovarian cancer." (PMID 24212946, 2011).